LILRB4 (leukocyte immunoglobulin like receptor B4)
Diseases named in the same sentence as LILRB4 in open-access papers (continued):
Sharing a sentence is not in itself a finding about the gene and the disease.
tumor (continued). "In particular, in solid tumors the blockade of LILRB4 with antibodies increases infiltrating anti-tumor immune cells and decreases the inhibitory immunosuppressive cells." (PMID 40433358, 2025). "Analysis using the BEST database revealed a significant increase in LILRB4 expression across various tumours, particularly in PCa, with its expression also elevated in paired PCa tissue samples." (PMID 40576161, 2025). "LILRB4 strongly suppresses tumour immunity in the TME, and as a result of this suppression, it limits anti-tumour efficacy in solid tumours." (PMID 40385641, 2025). "A similar reduction of GZMB/CCL5-expressing CD4+ TILs was observed when a comparison was made between 1956 tumour-bearing WT mice and mice with a targeted disruption of the Lilrb4 gene." (PMID 39048822, 2024). "LILRB4 is also expressed on the surface of tumor related macrophages, MDSC and other immune cells in the tumor microenvironment, forming a suppressive tumor microenvironment to promote tumor cell immune escape, and is a potential target for immunotherapy." (PMID 38951916, 2024). "Studies using LILRB4-/- mice and anti-LILRB4 antibody treatments confirm its pivotal role, reducing tumor burdens and improving survival rates." (PMID 38342925, 2024). "Functionally, LILRB4 also plays a crucial role in tumor metastasis by orchestrating myeloid-derived suppressor cells (MDSCs) and inhibiting miR-1 family miRNAs, further emphasizing its significance in disease progression." (PMID 38342925, 2024). "Adoptive transfer of HDVax-induced LILRB4+SEMA4a− or LILRB4+SEMA4a+ mItgb1-specific CD4+ T cells comparably ablated T3 tumour rejection in the Rag2−/− ACT assay." (PMID 39048822, 2024). "In order to clarify the expression pattern of LILRB4 in tumor cells, we queried LILRB4 expression in The Cancer Genome Atlas (TCGA) and The Human Protein Atlas database." (PMID 38951916, 2024). "Leukocyte Ig-like receptor B family 4 (LILRB4) as an immune checkpoint on myeloid cells is a potential target for tumor therapy." (PMID 38951916, 2024). "Binding of ApoE, one of the functional ligands of LILRB4, is coupled with T-cell suppression and tumor infiltration through LILRB4-mediated downstream signaling in AML cells." (PMID 38235377, 2024). "As a member of the immune checkpoint molecules, the role of LILRB4 in tumors is generally to promote tumor cell invasion and migration and to inhibit the proliferation and activation of immune cells such as T lymphocytes." (PMID 38397424, 2024). "Strikingly, the tumor sizes or weights derived from mice with LILRB4-knockdown MM cells were much smaller or less than those derived from mice with the scrambled cells." (PMID 39025844, 2024). "The activation of LILRB4 signaling enhances the development of an immunosuppressive microenvironment in mouse and human tumors and it facilitates the immune escape of tumor cells." (PMID 38954358, 2024). "The immune-related functions of LILRB4, coupled with its increasing relevance in tumour immunology, warrant further investigation into its role in tumour-immune dynamics and its potential for therapeutic targeting." (PMID 39457550, 2024). "LILRB4 was reported to support tumors through its dual functions as an immune checkpoint that suppresses T-cell proliferation and as a tumor-promoting molecule that enhances tumor migration." (PMID 38235377, 2024). "We detected the expression of LILRB4 in all kinds of tumor tissue arrays by immunohistochemistry (IHC)." (PMID 38951916, 2024). "Although different Lilrb4 inhibitors for anti-tumor therapy have emerged in pre-clinical studies, there are only a few studies on the effects of Lilrb4 on bone cells." (PMID 38892016, 2024). "By contrast, LILRB4 expression clearly identifies mouse Tr1-like cells from both the spleen and the tumour microenvironment." (PMID 39048822, 2024). "LILRB4 expressed on MDSCs has been shown to regulate the immunological function of MDSCs and facilitate tumor immune tolerance." (PMID 37461040, 2023).
tumor (continued). "Analysis of the tumour biopsies revealed that LILRA2, LILRA4, and LILRB4 were associated with the prognosis of PDAC patients." (PMID 36748687, 2023). "The potential mechanism is that LILRB4 changes the tumour microenvironment, resulting in immune suppression." (PMID 36748687, 2023). "LILRB4 blocking antibodies have demonstrated anti-tumor effects in solid tumor and hematological malignancies." (PMID 37662958, 2023). "LILRA2, LILRA4, and LILRB4 showed low expressions in tumour tissues, in which LILRB4 was significantly lowly expressed (p < 0.001)." (PMID 36748687, 2023). "Treatment of solid tumors with an antagonistic LILRB4 mAb or serum depletion of LILRB4 restored previously repressed antitumor T cell responses, further implicating a supportive role for LILRB4 in tumor development." (PMID 35076022, 2022). "LILRB4−/− genotype or LILRB4 blockade increased tumor immune infiltrates and the effector (Teff) to regulatory (Treg) T cell ratio and modulated phenotypes of TAMs toward less suppressive, CD4+ T cells to Th1 effector, and CD8+ T cells to less exhausted." (PMID 33974041, 2021). "LILRB4 was expressed on most tumor-infiltrating immune cell types, but the highest expression was on CD3+ T cell and CD11b+ cells." (PMID 33974041, 2021). "Correlation analysis of LILRB4 with various cell subsets in different cancer patients suggests that LILRB4 is expressed in most tumor-infiltrating immune cell types." (PMID 33974041, 2021). "We pooled mice from different experiments that were given monoclonal anti-LILRB4 antibody in primary MC38 tumor challenge, and survived." (PMID 33974041, 2021). "Similar to the B16F/10 tumor model, we observed a significant decrease in tumor burden and increase in survival in LILRB4−/− mice compared with WT control." (PMID 33974041, 2021). "There was also an increase in LILRB4 expression on CD3+ T cells with tumor progression (day 22 vs. day 32 tumor) in the RENCA tumor model." (PMID 33974041, 2021). "LILRB4 strongly suppresses tumor immunity, and LILRB4 blockade alleviates that suppression to provide antitumor efficacy." (PMID 33974041, 2021). "Although we looked at the expression of LILRB4 in various cancer patients, our survival and mechanistic studies were restricted to mouse tumor models; these experiments should be repeated in humanized murine models." (PMID 33974041, 2021). "We next explored the expression of LILRB4 on tumor-infiltrating immune cells from a variety of murine and human tumors by flow cytometry; it was highly expressed on CD45+ cells in most murine tumor models and cancer patients." (PMID 33974041, 2021). "We found a significant increase in both CD8+ T cell and CD4+ Teff cell to Treg cell ratios within tumor in anti-LILRB4–treated mice." (PMID 33974041, 2021). "Similar to the MC38 tumor, LILRB4 is expressed on most subsets of macrophages, with higher expression on TAMs with suppressive phenotype." (PMID 33974041, 2021). "As we observed LILRB4 expression in various tumor models, we wanted to know if LILRB4 functions as a negative regulator of tumor immunity across multiple models." (PMID 33974041, 2021). "We investigated the effect of LILRB4 on antitumor immunity in various murine tumor models by using antibody against this receptor and the LILRB4−/− mouse model." (PMID 33974041, 2021). "We explored the mechanisms of LILRB4 function using knockout mice and anti-LILRB4 antibody, and our findings suggest that LILRB4 inhibits tumor immunity through action on both myeloid and lymphoid compartments." (PMID 33974041, 2021). "The expression of LILRB4 increased on CD4+ T cells with tumor progression (day 22 versus day 14 tumors) after B16/F10 challenge." (PMID 33974041, 2021). "We next employed LILRB4−/− mice, which were described earlier, challenged them with B16/F10 tumor cells, and evaluated tumor burden and survival." (PMID 33974041, 2021).
tumor (continued). "In spite of the limitation of our survival studies to murine tumor models, our analysis of the LILRB4 expression in tumors of cancer patients and TCGA data suggests that LILRB4 has an important role to play in cancer patients as well." (PMID 33974041, 2021). "After tumor challenge, LILRB4−/− mice and mice treated with anti-LILRB4 antibody showed reduced tumor burden and increased survival." (PMID 33974041, 2021). "Almost 30% of mice that received anti-LILRB4 completely rejected tumors, and mice that did show tumor burden had delayed tumor growth." (PMID 33974041, 2021). "Lilrb4 RNA was expressed at an even higher level than Pdcd1, a known inhibitory receptor molecule, which is known to have a prominent role in tumor immunity." (PMID 33974041, 2021). "We have identified myeloid inhibitory receptor LILRB4 as a potential target for immunotherapy, aiming to modulate the intratumoral macrophage–T cell relationship from pro-tumor to anti-tumor." (PMID 33974041, 2021). "Phenotypic analysis by flow cytometry of TILs from B16/F10-challenged tumor suggests that LILRB4+CD4+ T cells expressed higher surface LAP/TGFβ compared with LILRB4−CD4+ T cells." (PMID 33974041, 2021). "To understand the extent of expression of LILRB4 in different tumor types, we analyzed RNA expression data from The Cancer Genome Atlas (TCGA) database." (PMID 33974041, 2021). "In this study, we found inhibitory receptor LILRB4 on a variety of intratumoral immune cell types in murine tumor models and human cancers, most prominently on TAMs." (PMID 33974041, 2021). "Taken together, these results reveal critical roles of LILRB4 in suppressing tumor immunity and its potential as a target for tumor immunotherapy." (PMID 33974041, 2021). "Third, aged Mb macrophages upregulate expression of immunosuppressive ligands Cd274/Pd-l1 and Lilrb4/Ilt3, thus, potentially inhibiting NK cells and T cells, creating a pro-tumor immune microenvironment." (PMID 33378681, 2020). "To verify whether BiKE enhances NK cell activity in mediating tumor cell killing, we co-cultured human PBMCs with LILRB4+ MM1.S cells." (PMID 41417876, 2025). "To investigate whether LILRB4 expression was responsible for creating an immunosuppressive TME, we explored the effects of LILRB4-immunotherapy on tumor progression in CRD mice by treating them with an anti-LILRB4 antibody." (PMID 41102383, 2025). "Furthermore, CAR-T therapy targeting LILRB4 has been shown to effectively eliminate MM cells and partially disrupts the immunosuppressive tumor microenvironment." (PMID 41417876, 2025). "Additionally, LILRB4 facilitates tumour metastasis by modulating myeloid‐derived suppressor cells, adjusting M2 polarisation and inhibiting the miR‐1 family." (PMID 40576161, 2025). "Notably, silencing LILRB4 not only promoted T cell maturation in spleen and lymph nodes but also enhanced T cell infiltration in tumor tissues." (PMID 41200716, 2025). "Tumor volumes were observed to be invariable across the treatment groups, but we observed a significant decrease (p < 0.0001) in the prevalence of lung metastasis in anti-LILRB4-antibody-treated mice under CRD." (PMID 41102383, 2025). "Furthermore, LILRB4 blockade increases tumour immune infiltrates and reduces exhausted CD8+ T cells in solid tumours." (PMID 40576161, 2025). "Thus, targeting LILRB4 with antibodies represents a tumor-specific and effective therapeutic strategy for treatment of monocytic AML." (PMID 38235377, 2024). "Therefore, targeting LILRB4 with monoclonal antibodies is an effective therapeutic strategy for the treatment of tumor diseases." (PMID 38397424, 2024). "In this study, we first focused on the expression of LILRB4 in various tumor tissue arrays." (PMID 38951916, 2024). "Interestingly, it has also been reported that many tumor cells, such as solid tumors and hematological tumors, highly express LILRB4." (PMID 39025844, 2024).
tumor (continued). "Blockade of LILRB4 enhances tumor immune infiltrates, rebalances effector to regulatory T cell ratios, and modulates TAM phenotypes toward a less suppressive state, promoting the transformation of CD4+ T cells into Th1 effectors and CD8+ T cells into less exhausted states." (PMID 38342925, 2024). "We next asked whether anti-LILRB4 treatment provoked phenotypic and/or functional changes in tumour-specific HDVax-induced Tr1 cells." (PMID 39048822, 2024). "Moreover, LILRB4 has been found on TAMs in several cancer types, and its blocking enhances the infiltration of anti-tumour immune cells due to the increased secretion of IL-1β and inducible nitric oxide synthase." (PMID 38022598, 2023). "Characterization of tumor immune cell infiltration in BRCA-ness demonstrated an association with suppressive tumor associated TREM2 macrophages expressing marker genes, such as LILRB4 and ITGB2, which were found to be downregulated by combination therapy." (PMID 37872395, 2023). "The authors of a recent study reported that LILRB4 plays a major role in regulating the immunosuppressive function of MDSCs by inhibiting the miR-1 family of microRNAs and facilitating tumor migration and invasion in the tumor microenvironment." (PMID 37461040, 2023). "In addition, LILRB4 expression on tumour-infiltrating cells and particularly MDSCs correlates with postoperative recurrence and shorter OS and relapse-free survival." (PMID 38022598, 2023). "LILRB4+ Tregs represent a small fraction of Foxp3+ cells in healthy peripheral blood but were found to be expanded in the circulation of allergic patients and in tumor infiltrating immune cells in various tumor models." (PMID 36591244, 2022). "We assessed the functional effect of anti-LILRB4 antibody treatment on tumor-infiltrating T cells." (PMID 33974041, 2021). "This agrees with our analysis of LILRB4 expression in murine models and tumor patients." (PMID 33974041, 2021). "To test the hypothesis that LILRB4 is a critical negative regulator of antitumor responses, we employed anti-LILRB4 polyclonal antibody in a tumor burden and survival experiment." (PMID 33974041, 2021). "Interestingly, applying powerful cytotoxicity to AML cells in vitro, decrement of xenograft model tumor burden in vivo, and reduction of off-tumor toxicity by sparing normal progenitors and HSPCs were found as results of using LILRB4-CAR T cell." (PMID 34412685, 2021). "Anti-LILRB4 antibody significantly decreased tumor weight compared with isotype control antibody." (PMID 33974041, 2021). "Genetic deletion of LILRB4 or anti-LILRB4 antibody treatment modulates T cells to an effector phenotype and TAMs to a less immunosuppressive phenotype and increases survival against tumor challenge." (PMID 33974041, 2021). "We used scRNA-seq to analyze the Lilrb4 expression in tumor-infiltrating CD45+ immune cells." (PMID 33974041, 2021). "Similarly, LILRB4 expression on DCs drives the differentiation of naïve T cells into regulatory T cells (Tregs) and T suppressor cells (Ts), contributing to an immunosuppressive tumor microenvironment (TME)." (PMID 41102383, 2025). "Moreover, T3 tumours grew progressively in WT mice treated with T3-HDVax and control monoclonal antibody, but were rejected in WT mice receiving the combination of T3-HDVax + anti-LILRB4." (PMID 39048822, 2024). "However, there are exceptions, suggesting that LILRB4 may also play a tumor-suppressive role in tumor development, such as in chronic lymphocytic leukemia (CLL), where LILRB4 is ectopically expressed and a selective marker for CLL malignancy." (PMID 38397424, 2024). "However, inconsistent with the results of other tumours, high expressions of LILRB2 and LILRB4 were associated with better clinical outcomes in our study, while other studies showed that patients with high expressions of LILRB2 and LILRB4 predicted worse clinical outcomes." (PMID 36748687, 2023).
tumor (continued). "In addition to proliferation, apoptosis, invasion and metastasis, and metabolic reprogramming, m6A modification can also interfere with the immune escape of tumor cells by regulating the presentation ability of dendritic cells and affecting the expression of immune checkpoint genes (LILRB4)." (PMID 33926508, 2021). "In this study, we designed a carrier-free “3-in-1” peptide–daunorubicin–siRNA (PDR) nanoassembly, which combines a cell-penetrating and tumor-suppressing peptide, a daunorubicin (DNR) prodrug, and siRNA targeting the LILRB4 gene." (PMID 41200716, 2025). "In our study, BiKE: LILRB4/CD16A was developed, which specifically links NK cells with LILRB4-positive MM cells to facilitate tumor cell killing." (PMID 41417876, 2025). "LILRB4, which is expressed on MM and Myeloid-Derived Suppressor Cells (MDSC) and plays an important role in promoting tumor progression and regulating the immuno-suppressive microenvironment." (PMID 41417876, 2025). "We found that LILRB4 blockade effectively decreased ARP-1 growth in vivo, as exhibited by reduced tumor size and volume compared to those in the control group." (PMID 39025844, 2024). "LILRB4 blockade restored IL-2 production in HDVax-induced cells and enhanced their expression of IFNγ/TNF and CD40L in both T3 and F244 tumour models." (PMID 39048822, 2024). "Leukocyte immunoglobulin-like receptor subfamily B member 4 (LILRB4) orchestrates polarization of M-MDSCs and suppresses the secretion of miR-1 family miRNAs, facilitating tumor migration and invasion." (PMID 37443711, 2023). "We also found LILRB4 expression to be highly correlated with other inhibitory molecules, specifically PDCD1 (PD1) and HAVCR2 (TIM3), in different tumor types." (PMID 33974041, 2021). "To comprehensively profile the LILRB4 expression on intratumoral myeloid cells, we used a myeloid-focused CyTOF panel and MC38 tumor model." (PMID 33974041, 2021). "The xenograft model confirmed that LILRB4 inhibition significantly reduced tumour weight and slowed tumour growth, with no significant change in the mice's body weight." (PMID 40576161, 2025). "Additionally, LILRB4 demonstrated upregulation on CD45+ immune infiltrates, with expression levels increasing progressively during tumor advancement." (PMID 40860159, 2025). "Moreover, the recipient mice receiving PFKFB1-overexpressing LILRB4-knockdown ARP-1 cells had enhanced growth capability compared with that of the LILRB4-knockdown ARP-1 mice, as exhibited by the increased tumor sizes and tumor weights." (PMID 39025844, 2024). "High TPS was associated with genes such as SOX11 and GSX1, which may promote tumour proliferation, whereas Low TPS was enriched with immune-related genes like LILRB4, highlighting the complex interactions within the tumour microenvironment." (PMID 39457550, 2024). "Although LILRB4 expression inhibits Akt kinase activation upon B-cell receptor (BCR) stimulation, it can functionally contribute to the regulatory network controlling tumor progression by inhibiting the Akt pathway." (PMID 38397424, 2024). "LILRB4 play crucial roles in affecting the clinical outcomes of early‐stage PDAC through JAK‐STAT signalling pathway, immune‐related signalling pathways, and tumour‐infiltrating immune cells." (PMID 36748687, 2023). "In a recent study it was shown that LILRB4 interactions with fibronectin are capable of polarizing or maintaining DCs in the TME and draining lymph nodes in an immunosuppressive state, ultimately leading to decreased T cell activation and anti-tumor activity." (PMID 37662958, 2023). "Like LILRB2, LILRB4 has been reported to control NSCLC pathogenesis, enhancing widespread NSCLC cell invasion and tumor angiogenesis, and may serve as an alternative strategy for NSCLC treatment." (PMID 35076022, 2022).